NOX4 (NADPH oxidase 4)
Diseases named in the same sentence as NOX4 in open-access papers (continued):
Sharing a sentence is not in itself a finding about the gene and the disease.
pulmonary hypertension (33 papers, 2012 to 2024). Increased pressure within the pulmonary circulation due to lung or heart disorder. "In contrast, increased expression of HDAC3, HDAC4, and HDAC5 is associated with induction of Nox2 and Nox4 in pulmonary arterial hypertension, which was decreased by the HDAC inhibitor, valproic acid." (PMID 31223486, 2019). "Regarding the possible role of pulmonary arterial hypoxia and ischemia reperfusion in PH development, it has been reported that in patients with idiopathic pulmonary hypertension, NOX4 induces the vascular remodelling associated with this disease in response to chronic hypoxia." (PMID 34359380, 2021). "In another mouse model, chronic intermittent hypoxia (CIH)-induced pulmonary hypertension is associated with increased lung levels of the NOX4 and p22phox, reduced NO bioavailability, increased activity of platelet-derived growth factor receptor β (PDGFRβ) and downstream effector, Akt kinase." (PMID 28594389, 2017). "In conclusion, we found that daily intermittent short-duration reoxygenation partially prevented pulmonary hypertension through regulating the NOX4/H2O2/PPAR-γ axis in PASMCs." (PMID 38237016, 2024). "Other studies showed the upregulation of NOX4 in hypoxic pulmonary artery smooth muscle cells and animal models of hypoxia-induced pulmonary hypertension." (PMID 39456432, 2024). "NOX2 and NOX4 levels are elevated in pulmonary artery hypertension (PAH), and its blockage has shown to revere PAH in animal models." (PMID 35783193, 2022). "An excessive expression of NOX4 was reported in pulmonary diseases, including pulmonary fibrosis, pulmonary hypertension, and COPD." (PMID 34829671, 2021). "Some studies have reported elevated levels of NOX4 in airway smooth muscle of COPD patients, which were found to correlate with disease severity and to be associated with pulmonary hypertension." (PMID 34829671, 2021). "The NOX4-derived reactive oxygen species production is likely to play a role in the pulmonary hypertension development in chronic obstructive pulmonary disease." (PMID 34440716, 2021). "Endothelial Nox4 influences angiogenesis and vascular aging, and perivascular Nox4 is important in vascular remodeling in pulmonary hypertension." (PMID 30334629, 2019). "Administration of HDAC inhibitors reduced the expression of Nox2 and Nox4 in monocrotaline-induced pulmonary hypertension." (PMID 30830950, 2019). "Nox4-derived ROS contributes to oxidative and ER stress through oxidation of proteins that influence vascular function in pulmonary hypertension." (PMID 31239370, 2019). "In the monocrotaline-induced pulmonary hypertension rat model, Nox4 expression is induced in cardiomyocytes but also in the intercellular area (mainly co-localizing with fibroblasts)." (PMID 30618811, 2018). "In the RV, NOX4 is also regulated by the α1A-receptor; stimulation of this receptor decreases NOX4 expression during pulmonary hypertension." (PMID 30618811, 2018). "To investigate the pathophysiological significance of estrogen–Nox–dependent processes in PAH, we studied female Nox1−/− and Nox4−/− mice with pulmonary hypertension." (PMID 27402919, 2016). "To evaluate the pathophysiological significance of our in vitro findings, we extended our studies to an estrogen-dependent mouse model of pulmonary hypertension by examining female Nox1−/− and Nox4−/− mice exposed to hypoxic conditions." (PMID 27402919, 2016). "IH-induced pulmonary hypertension in mice leads to increased lung levels of the NADPH oxidase subunits NOX4 and p22phox, indicating that NADPH oxidase-derived ROS contributes to the development of pulmonary hypertension caused by chronic intermittent hypoxia." (PMID 24734153, 2014). "This indicated that NOX4, as an important factor, is involved in pulmonary vascular remodeling during pulmonary hypertension development." (PMID 25203114, 2014).
pulmonary hypertension (continued). "In the lung tissue specimens of patients with idiopathic pulmonary hypertension, NOX4 was significantly increased, mainly localized in the blood vessel membranes." (PMID 25203114, 2014). "It would also be important to assess a role for Nox4 in additional models such as the rat which develop a more robust pulmonary hypertension that is closer to the human condition." (PMID 23125837, 2012). "We found that intermittent short-duration reoxygenation relieved pulmonary hypertension via NOX4/H2O2/PPAR-γ axis and further reducing non-NOX4 dereived H2O2 could further alleviated hypoxic pulmonary hypertension." (PMID 38237016, 2024). "Thus, hypoxia has been shown to induce NOX4 in kidney, brain, lung, pulmonary artery smooth muscle cells, and adventitial fibroblasts from patients with pulmonary arterial hypertension." (PMID 39456432, 2024). "TGF-β promotes SMC proliferation through upregulation of the Nox4 expression, which is the main isoform expressed in PASMCs of patients with pulmonary hypertension, and Nox4 may affect VSMC proliferation by promoting ROS production." (PMID 36593773, 2022). "However, studies in both patients with other pathologies and mice with pulmonary hypertension induced by exposure to chronic hypoxia have revealed overexpression of the Nox4 isoform." (PMID 35805984, 2022). "Nox4 could play an important role in the PASMC proliferation under hypobaric hypoxia-induced pulmonary hypertension." (PMID 34434114, 2021). "NOX4-derived reactive oxygen species production may play a role in the pulmonary hypertension development in chronic obstructive pulmonary disease." (PMID 34440716, 2021). "Collectively, these findings indicate that functional interference with NOX4 may provide a novel therapeutic approach for the treatment of attenuate hypoxia-induced pulmonary hypertension." (PMID 28594389, 2017). "Similarly, hypoxia inhibits TRX2 expression, but promotes NOX4 expression of pulmonary hypertension." (PMID 28594389, 2017). "Furthermore, under hypoxia-induced pulmonary hypertension conditions, rosiglitazone prevents and reverses pulmonary hypertension by downregulating Nox4." (PMID 22778711, 2012). "The results showed that intermittent 3-h/per day reoxygenation (I3) effectively attenuated chronic hypoxia-induced pulmonary hypertension and reduced the content of H2O2 and the expression of NADPH oxidase 4 (NOX4) in lung tissues." (PMID 38237016, 2024). "(2019) during an in vivo and in vitro investigation shows that treatment of pulmonary hypertensive rats and PASMCs with magnesium lithospermate B reduces the expression of NOX2 and NOX4 and ERK in PAs, also reduces the ROS and H2O2 levels." (PMID 32226378, 2020). "The NADPH oxidase complex (specifically the Nox4 isoform) is considered to be a principal source of vascular pulmonary artery ROS production, which may be related to PASMC proliferation and pulmonary hypertension induced by hypobaric hypoxia." (PMID 35204150, 2022). "In addition, studies on PASMCs under normobaric hypoxia in both humans and animals have shown that the NADPH oxidase complex (specifically the Nox4 isoform) is overexpressed, contributing to PASMC proliferation leading to pulmonary hypertension." (PMID 34434114, 2021). "In support of the importance of Nox1 in vascular processes associated with pulmonary hypertension, our in vivo studies showed that hypoxia-induced pulmonary hypertension and arterial remodeling were ameliorated in Nox1−/− mice but not in Nox4−/− mice." (PMID 27402919, 2016). "Whether pulmonary hypertension and remodeling of pulmonary arterioles and the right ventricle in response to chronic hypoxia is altered in the Nox4 knockout mouse is not yet known." (PMID 23125837, 2012).
gastric cancer (32 papers, 2017 to 2026). A primary or metastatic malignant neoplasm involving the stomach. "The hub gene-based risk model (DUSP1/TNF/NOX4/LONP1) shows promise as an overall survival predictor in gastric cancer." (PMID 38758860, 2024). "As an important ROS-producing enzyme, theexpression of NOX4 in gastric cancer cells is closely related to ROSlevels." (PMID 41505409, 2026). "Given the elevated NOX4 expression and ROS accumulationin gastric cancer, Zn-Quer NZs enable targeted and controlled drugdelivery to tissues, effectively mitigating oxidative-stress-inducedcell inflammation and malignant transformation." (PMID 41505409, 2026). "Among this select group of genes, we deliberately chose NOX4 for further investigation due to its well-documented role as a tumor promoter in gastric cancer." (PMID 39991587, 2025). "In this study, we demonstrated 8-shogaol’s role in modulating anti-cancer and anti-inflammatory efficacy mediated by NOX4-induced ER stress signaling pathways and apoptosis in gastric cancer." (PMID 39796030, 2024). "Silencing NOX4 or ROS inhibitors (DPI or NAC) treatment inhibited the increases in ROS, cytotoxicity, and caspase-3 activity in 8-shogaol-treated gastric cancer cells, meaning NOX4 as the regulator of 8-shogaol-mediated ROS production." (PMID 39796030, 2024). "Whereas the regulation of ROS by PF was bidirectional, on the one hand, in cancer cells, it ameliorates gastric cancer by boosted downstream apoptosis through mediated Nox4-regulated ferroptosis." (PMID 39244559, 2024). "This study indicates that PF, an anti-inflammatory reagent, blocks cancer cell proliferation and growth by regulating cell death, apoptosis, and Nox4-mediated ER stress response in gastric cancer cells in vivo and in vitro." (PMID 38140352, 2023). "Next, to further validate the roles of FIRGs in the development of gastric cancer, we silenced GPX3, SPARC and NOX4 in gastric cancer cell lines MGC803 and MKN45 to examine the effects on the cell viability, proliferation and migration/invasion." (PMID 38021154, 2023). "It was recently reported that the expression of NOX4 is closely related to the tumor size and prognosis in gastric cancer; the prognosis of colorectal cancer patients with high expression of NOX4 was poor." (PMID 33153467, 2020). "NOX4 depletion inhibits gastric cancer survival in blood circulation and attenuates distant metastasis." (PMID 30237423, 2018). "In a Chinese study, Nox4 expression was correlated with tumor size and poor prognosis in 90 patients with gastric cancer and knockdown of NOX4 expression blocked cell proliferation and the expression of Cyclin D1, BAX and so on in vitro." (PMID 30513726, 2018). "When it comes to gastric cancer, all three studies related to NOX4 and gastric cancer displayed a tumor promoter role of NOX444–46." (PMID 30237423, 2018). "Moreover, the treatment increased the production of ROS and intracellular Ca2+ and upregulated NOX4 in gastric cancer cells." (PMID 39796030, 2024). "In addition, NOX4 is also one of the marker genes of immune infiltration, and is highly correlated with the prediction of gastric cancer immunotherapy, the pathogenesis of keloid disorder, and the clinical outcome of colon cancer." (PMID 36911415, 2023). "Importantly, studies have shown that NOX4 plays an important role in the growth and apoptosis of gastric cancer cells by producing ROS and activating GLI1 signaling." (PMID 35528617, 2022). "Nox4 is closely correlated with gastric cancer progression and predicts a poor prognosis." (PMID 35293283, 2022). "The target gene NOX4 plays a key role in the development of gastric cancer." (PMID 33193668, 2020). "To further explore the clinical correlation between NOX4 and EGFR expression in gastric cancer patients, we examined NOX4 expression in gastric cancer tissues and the paired adjacent normal tissues from 90 patients by IHC using anti-EGFR or anti-NOX4 antibodies." (PMID 30237423, 2018).
gastric cancer (continued). "Interestingly, EGFR expression was increased in 68.42% (39/57) of NOX4-positive gastric cancer patients." (PMID 30237423, 2018). "Nox4 also plays a crucial role in regulating gastric cancer cell growth." (PMID 30513726, 2018). "NADPH oxidase 4 (NOX4) expression and ROS generation are up-regulated in some tumors such as gastric cancer, leading to anoikis resistance by inducing EGFR activation." (PMID 41596231, 2026). "In gastric cancer cell models, DPI alleviated oxidative stress by inhibiting NOX4 expression and ROS production." (PMID 41012715, 2025). "The NRGPI effectively predicts prognosis and immunotherapy efficiency in cases of gastric cancer by measuring AXL, RAI14, and NOX4 levels." (PMID 39570876, 2024). "The knockdown of Nox4 suppressed the reduction in cell viability and LDH release in the PF-treated gastric cancer cell lines AGS and SNU-638 compared with the control groups." (PMID 38140352, 2023). "NOX4 (logFC = 1.948, P = 4.55e-12), COL8A1 (logFC = 1.982, P = 1.22e-8) and CHST1 (logFC = 1.783, P = 9.04e-13) were significantly upregulated in gastric cancer tissues." (PMID 33193668, 2020). "Among these, the selection of 19 HERSRDEGs such as ANGPT2, ERG1, CD36, NOX4 and TLR2, provides critical insights into the potential roles these genes may play in gastric cancer pathophysiology." (PMID 40061897, 2025). "Moreover, high expression of NOX4 and NOX5 were correlated to poorer overall survival in patients with end-stage gastric cancer." (PMID 38542437, 2024). "NOX4 silencing or ROS inhibitor (NAC or DPI) treatment inhibited the increase in ROS, caspase-3 activity, cytotoxicity, and the PERK-ATF4-CHOP signaling pathway in 8-shogaol-treated gastric cancer cells." (PMID 39796030, 2024). "To confirm our speculation, we used R scripts and website tools to conduct several bioinformatics analyses to investigate the clinicobiological function of CHAC1, NOX4 and HIF1A and the therapeutic potential of CHAC1, NOX4 and HIF1A in stomach cancer." (PMID 35023280, 2022). "NOX4 can support glycolysis and promote glutamine metabolism in non-small cell lung cancer (NSCLC) cells and drive ROS formation via GLI1 pathway to regulate gastric cancer cell proliferation and apoptosis." (PMID 35293283, 2022). "In the cohort from the GEPIA database, the expression of NOX4, COL8A1, and CHST1 in gastric cancer tissues was higher than that in normal tissues, and the expression levels of NOX4 (F = 5.67 and P = 0.0008) and COL8A1 (F = 6.49 and P = 0.0003) differed across the four pathological stages." (PMID 33193668, 2020). "Contrary to the results of this study, increased expression of four genes (CLIP4, NOX4, LAMP5, and MATN3) is related to poor prognosis, and the expression of these genes is higher in stromal components than in epithelial cancer cells in gastric cancer." (PMID 33575272, 2020). "In conclusion, induction of NOX4 expression by detachment promotes anoikis resistance of gastric cancer through ROS generation and downstream upregulation of EGFR, which is critical for the metastatic progression of gastric cancer." (PMID 30237423, 2018). "Our data revealed that anoikis-resistant GC cells acquired stronger proliferative and invasive properties compared with nonresistant gastric cancer cells, and these properties were attenuated by NOX4 depletion." (PMID 30237423, 2018). "Nicotinamide adenine dinucleotide phosphate (NADPH) oxidase 4 (NOX4), a subunit of the NOX complex, has been demonstrated to drive reactive oxygen species generation, in turn contributing to cell proliferation and apoptosis of gastric cancer cells via activation of the GLI1 pathway." (PMID 38021154, 2023). "In addition, the expression of the target genes NOX4, COL8A1 and CHST1 in the brown module was upregulated in gastric cancer, and these genes could predict the prognosis of gastric cancer patients, as verified in 3 independent cohorts." (PMID 33193668, 2020).
gastric cancer (continued). "Moreover, NOX4 expression is positively correlated with EGFR expression, which might convert them as promising biomarkers of gastric cancer for the clinics." (PMID 30237423, 2018). "Therefore, NOX4 might be constitutively active upon detachment from the ECM, likely forming a self-perpetuating loop in gastric cancer cells." (PMID 30237423, 2018). "NADPH oxidase 4 (NOX4) transmits electrons for various redox reactions by generating reactive oxygen species (ROS), which are present at high levels in a variety of malignant tumors, including gastric cancer (GC)." (PMID 42157942, 2026). "Intersection genes TREM2, CTHRC1, BGN, NOX4, GPX3, HEYL, and SFRP4 from the GSE72305 and GSE103236 datasets, which were differentially expressed in the normal gastric mucosa than in gastric cancer cells and in lymph node free to lymph node metastatic GC." (PMID 33976737, 2021). "The effect of NOX-enhanced tumor metastasis in gastric cancer could be mediated through regulation of EMT markers, including MMPs, fibronectin, vimentin, snail, zeb1, and E-cadherin 62, which is consistent with our findings that MMP expression was essential for NOX4-regulated CRC cell invasion." (PMID 32641980, 2020).